LINC02280 (long independently transcribed non-coding RNA 2280)
Gene: Long non-coding RNA gene on chromosome 14 (104,661,120 to 104,665,558, reverse strand). Ensembl gene ENSG00000260792.
Diseases named in the same sentence as LINC02280 in open-access papers:
LINC02280 is named in the same sentence as 1 disease in open-access papers, as found by Europe PMC text mining. Sharing a sentence is not in itself a finding about the gene and the disease.
LINC02280 shares sentences with these, for which no sentence is quoted: liver cancer (1 paper).